YAP1 (Yes1 associated transcriptional regulator)
Diseases named in the same sentence as YAP1 in open-access papers (continued):
Sharing a sentence is not in itself a finding about the gene and the disease.
glioma (continued). "In 214 cases of glioma, Pearson’s correlation analysis was performed to clarify the associations among MT1-MMP, β1-integrin and YAP1." (PMID 35350840, 2022). "Dipyridamole impaired autophagic flux and rendered glioma cells more vulnerable to apoptotic cell death through ER stress-inhibitable YAP1/autophagy axis." (PMID 35054765, 2022). "Clinical studies have revealed that YAP1 is a reliable prognostic biomarker and therapeutic target of glioma." (PMID 35054765, 2022). "YAP1’s up-regulated molecular pathway in glioma is the most feasible molecular target that needs to be broken in the future to improve the treatment processes of glioma." (PMID 35935338, 2022). "Our findings reveal that a reduction of YAP1 due to dipyridamole, involving the ER stress-mediated phosphorylatory mechanism, leads to impaired autophagic flux and augmented apoptosis in glioma cells." (PMID 35054765, 2022). "Dipyridamole impairs autophagic flux and renders glioma cells more vulnerable to apoptotic cell death through the ER stress-inhibitable YAP1/autophagy axis." (PMID 35054765, 2022). "The increase in ROS can also affect the apoptosis and metabolism of glioma cells via the JNK-regulated metabolic pathway and ataxia telangiectasia mutated (ATM)-Yes-associated protein 1 (YAP1)-driven apoptotic pathway." (PMID 35935861, 2022). "A recent study has reported that imipramine impedes glioma progression with concurrent cAMP elevation and YAP1 inhibition." (PMID 35054765, 2022). "The Co-IP assay confirmed direct interaction of YAP1 with TEAD4 in glioma cells cultured in a flask." (PMID 33408794, 2021). "YAP1 is a key effector of the Hippo pathway and has emerged as a significant determinant of malignancy in glioma." (PMID 33336871, 2021). "The rescue assays confirmed that inhibiting linc00475 restrained the progression of glioma through the miR‐141‐3p/YAP1 pathway." (PMID 33336871, 2021). "Together, these results suggested that the integrin αvβ3/CDC42/F-actin/YAP-1/NUPR1/Nestin signaling pathway was activated in 3D collagen/FN cultured glioma cells and induced glioma cell proliferation." (PMID 33408794, 2021). "YAP1 promotes cell competition in glioma by decreasing apoptosis, and knock‐down of YAP1 attenuates self‐renewal capability." (PMID 33336871, 2021). "Expectedly, the expression of YAP1 was down‐regulated after knock‐down of linc00475 in glioma cells." (PMID 33336871, 2021). "In a study of 117 glioma tissues, high YAP1 protein expression was previously correlated with more aggressive glioma phenotypes and survival." (PMID 34771529, 2021). "It was observed that DLGAP1-AS2 was overexpressed in glioma and upregulated YAP1 to promote glioma cell proliferation and metastasis." (PMID 34454450, 2021). "Higher YAP1 expression was significantly associated with poorer overall survival and disease-free survival in adrenocortical carcinoma (ACC), brain Lower Grade Glioma (LGG), and pancreatic adenocarcinoma (PAAD)." (PMID 34257617, 2021). "Our study proved that miR‐141‐3p was expressed at low levels in glioma and was involved in the regulation of linc00475 by acting as a sponge for YAP1." (PMID 33336871, 2021). "mRNA levels of the independent predictors coherently correlate with YAP1 in glioma, kidney renal clear cell, head and neck, and bladder cancer." (PMID 30006603, 2018). "It has been well-established that YAP1 activation is crucial for glioma cell invasion and proliferation." (PMID 28548934, 2017). "In a continued effort to identify genes that are specifically associated with the survival of IDH-mutant gliomas, we examined IGFBP2, WWTR1, and YAP1, which are associated with glioma progression." (PMID 27852048, 2017). "This suggests that PP1γ expression may influence the expression of YAP1 and SOX2, and is associated with the growth and malignant progression of glioma." (PMID 40626009, 2025).
glioma (continued). "Nuclear localization of YAP1 was also higher in leader than follower cells in DMG lines PBT-24 and PBT-29, suggesting that YAP1 nuclear localization may be a common feature of leader cells during pediatric glioma migration." (PMID 38477830, 2024). "The impact of YAP‐1 on glioma prognosis was examined in a different investigation." (PMID 38925618, 2024). "For example, suppressing YAP1 expression reduces N-cadherin expression in glioma cells." (PMID 38308096, 2024). "YAP1 is highly expressed in human glioma, and it may serve as a reliable prognostic biomarker and therapeutic target for glioma." (PMID 38730506, 2024). "Also, we found that lncRNA NUTM2A-AS1 positively regulates of YAP1 expression in human glioma cells." (PMID 38730506, 2024). "Similarly, other studies found a correlation between the expression of the MT1-MMP, Beta1-integrin, YAP1 pathways and the grading of gliomas." (PMID 36980765, 2023). "In summary, this suggested that MT1-MMP and YAP1 may be a prognostic factor and therapeutic target by affecting the molecular typing of glioma." (PMID 35350840, 2022). "Thus, this study suggested that MT1-MMP, β1-integrin and YAP1, as tumor suppressors, are expected to be promising prognostic biomarkers and therapeutic targets for glioma patients." (PMID 35350840, 2022). "YAP1 also regulates the glioma phenotype by inhibiting proneural marker OLIG2 expression." (PMID 36046036, 2022). "YAP1 promoted autophagy and protected glioma cells from dipyridamole-induced apoptotic cell death." (PMID 35054765, 2022). "The down-regulation of YAP1 can be potentially helpful to develop new treatment methods for glioma." (PMID 35935338, 2022). "As YAP1 is a transcriptional coactivator that shuttles between the cytoplasm and nucleus, we evaluated both its cytoplasmic and nuclear expression in the human glioma specimens." (PMID 35350840, 2022). "Whether this conclusion cannot infer that there is a carcinogenic signal pathway of MT1-MMP/β1-integrin/YAP1 in gliomas needs further study." (PMID 35350840, 2022). "Moreover, circNEIL3-overexpressing glioma cells drive macrophage infiltration into the TME by activating YAP1 signalling." (PMID 35031058, 2022). "Analysis on public glioma databases revealed higher expression of YAP1 in mesenchymal subtype than other subtypes and shortened survival of patients with high YAP1 expression compared to those with low YAP1 expression." (PMID 34987659, 2022). "Moreover, circNEIL3-overexpressing glioma cells drive macrophage infiltration into the TME by activating YAP1 signalling and secreting CCL2 and LOX, which are strong macrophage chemokines." (PMID 35031058, 2022). "It is concluded that Yap1 inhibitor may become an effective target for the treatment of glioma in the near future through efforts of generation after generation." (PMID 35935338, 2022). "It was suggested that MT1-MMP, β1-integrin and YAP1 might promote the proliferation of glioma cells and eventually lead to the malignant progression of gliomas." (PMID 35350840, 2022). "With the further growth in YAP1 expression, the invasive trait of glioma also raises." (PMID 35935338, 2022). "However, there are a few reports on the expression of YAP1 in gliomas and its correlation with MT1-MMP." (PMID 35350840, 2022). "We performed rescue assays to confirm whether miR‐141‐3p and YAP1 are involved in linc00475‐mediated glioma development." (PMID 33336871, 2021). "Knock‐down of linc00475 inhibited tumorigenesis of glioma through the miR‐141‐3p/YAP1 pathway." (PMID 33336871, 2021). "This study illustrates that miR‐141‐3p inhibits tumorigenesis of glioma by targeting YAP1." (PMID 33336871, 2021). "Taken together, the linc00475/miR‐141‐3p/YAP1 axis provides a promising target for glioma therapy." (PMID 33336871, 2021). "Mass spectrometry analysis showed that TEAD4 may be the main binding partner for YAP1 as a co‐activator protein in glioma." (PMID 33408794, 2021).
glioma (continued). "Similarly, DLGAP1-AS2 modulated glioma cell proliferation, migration and apoptosis by regulating YAP1." (PMID 33517850, 2021). "Furthermore, oncogenic YAP1 activation occurs as a consequence of a loss in NF2-dependent inactivation of LATS1 (a key inhibitor of YAP1), and decreased LATS1 activity has also been associated with glioma progression." (PMID 29440180, 2018). "Interestingly, YAP1 expression in the glioma cell nucleus transfected with IKBKE-shRNA was reduced much more than in the cytoplasm." (PMID 28548934, 2017). "In addition, lncRNA NUTM2A-AS1 positively regulated of YAP1 expression in glioma cells." (PMID 38730506, 2024). "Thus, lncRNA NUTM2A-AS1 may regulate the proliferation and apoptosis of glioma cells through the miR-376a-3p/YAP1 axis." (PMID 38730506, 2024). "Therefore, we speculate that the lncRNA NUTM2A-AS1 may regulate the malignant biological behavior of glioma cells by regulating the miR-376a-3p/YAP1 axis." (PMID 38730506, 2024). "Finally, we investigated the relationship between lncRNA NUTM2A AS1 and YAP1 in human glioma cells." (PMID 38730506, 2024). "Moreover, YAP1 expression consistently predicted worse prognosis in several glioma databases." (PMID 34987659, 2022). "Nevertheless, whether YAP1 is the target of miR‐141‐3p in glioma is poorly defined." (PMID 33336871, 2021). "To further explore whether the Hippo pathway could influence epithelial-mesenchymal transition (EMT) in glioma cell lines, we first designed siRNA to respectively downregulate the expression of YAP1 and TEAD2, two important downstream factors of the Hippo pathway." (PMID 28548934, 2017). "SIRT1 overexpression upregulates YAP1 and VEGF, promoting glioma cell proliferation, migration, and angiogenesis." (PMID 40710366, 2025). "Here, we found that WWP2 knockdown‐mediated reduction of WWP2 and YAP1 expression and elevation of LATS2 and p‐YAP1 levels in glioma cells was reversed by the combination of sh‐WWP2 and sh‐CMTM5 transfection." (PMID 39166861, 2024). "Previous study explored the TMSB10 promoted glioma progression via YAP1/AKT/ERK1/2, but we explored the TMSB10 promoted glioma progression via IL6/JAK/STAT3 signaling pathway." (PMID 37275863, 2023). "In glioma cells, NF2 is phosphorylated and inactivated, which upregulates YAP1 expression and mediates the activation of epidermal growth factor receptor and Notch signalling pathways, promoting glioma cell proliferation and tumour formation." (PMID 37423952, 2023). "The expression of IGF2BP3, YAP1, CD68 (human macrophage marker) was enhanced in circNEIL3-high glioma tissues compared to circNEIL3-low tissues." (PMID 35031058, 2022). "In dipyridamole-treated glioma cells, the levels of PERK/eIF2α phosphorylation paralleled with YAP1 phosphorylation and YAP1 reduction, while the pharmacological and genetic inhibition of ER stress alleviated dipyridamole-induced changes in YAP1." (PMID 35054765, 2022). "In one study, expression of YAP1/TAZ and their target gene, BIRC5, was positively correlated with the prognosis of glioma patients, with subsequent downregulation of large tumor suppressors 1/2 (LATS1/2)-associated pathways." (PMID 35884733, 2022). "Our study provided evidence suggesting that collagen and FN collaborate to facilitate proliferation and tumorigenesis of glioma cells through the PI3K/AKT/SOX2 and CDC42/F-actin/YAP-1/Nupr1/Nestin pro-survival signaling networks." (PMID 33408794, 2021).
glioma (continued). "We provided evidence that collagen/FN complex regulates glioma stemness via an integrin αvβ3-activated PI3K/AKT/SOX2 and CDC42/F-actin/YAP-1/Nupr1/Nestin signaling network." (PMID 33408794, 2021). "We observed reduced nuclear but elevated cytoplasmic YAP-1 in the 3D collagen/FN-cultured glioma cells, whereas integrin αvβ3 suppression or CDC42 overexpression significantly increased the YAP-1 expression in the nucleus." (PMID 33408794, 2021). "Our pervious study also identified that YAP1/TAZ increased and meanwhile those of p-YAP1/p-TAZ and LATS1/2 decreased in gliomas." (PMID 28962630, 2017). "As expected, IDH-mutant gliomas manifested increased methylation concomitant with decreased expression of IGFBP2, YAP1, and WWTR1 in comparison with IDH-wildtype." (PMID 27852048, 2017). "Furthermore, YAP1 positively correlated with IGF1R gene expression in GBM in both the TCGA and Chinese Glioma Genome Atlas (CGGA) datasets." (PMID 41510300, 2025). "Similar to YAP1, TAZ expression is elevated in high-grade gliomas." (PMID 37423952, 2023). "We found that glioma cells with YAP1 depletion showed decreased viability without signs of caspase 3 activation." (PMID 35054765, 2022). "More importantly, we identified that collagen/FN stimulated glioma progression through integrin αvβ3-induced PI3K/AKT/SOX2 and CDC42/F-actin/YAP-1/Nupr1/Nestin double signal activation simultaneously, expounding the underlying mechanism of the extracellular matrix-induced tumor signaling network." (PMID 33408794, 2021). "In addition, we verified that CYT387 increased Hippo pathway activity to inhibit glioma malignancy and that IKBKE directly interacted with YAP1 and TEAD2, as determined by using coimmunoprecipitation (co-IP)." (PMID 34544426, 2021). "By regulating the miR-141-3p/YAP1 axis, LINC00475 facilitates tumor progression of glioma." (PMID 34950662, 2021). "Additionally, the same correlations were found between YAP1 expression and unfavorable OS and DFS in patients with glioma, as well as shorter OS in esophageal carcinoma patients and better DFS in bladder urothelial carcinoma patients." (PMID 31613226, 2019). "YAP1/TAZ-BIRC5 might be abnormally activated due to LATS1/2 down-regulation, which in turn promotes the occurrence and development of gliomas." (PMID 28962630, 2017). "This suggests that the lack of correlation between HDACi resistance and YAP1 expression in our parental cultures might be explained by the very low expression of YAP1 in all but 2 of 9 of our glioma cultures." (PMID 41066183, 2025). "Besides, the clinical relevance of the miR-376a-3p/NUTM2A-AS1/YAP1 axis in glioma was not investigated." (PMID 38730506, 2024). "YAP1 was positive in 134 cases and negative in 80 cases of glioma." (PMID 35350840, 2022). "The expression level of YAP1 and recurring could also predict the PFS in glioma." (PMID 35350840, 2022). "Furthermore, we found YAP1 overexpression might indicate unfavorable OS and DFS in patients with glioma, as well as worse OS in esophageal carcinoma patients and better DFS in bladder urothelial carcinoma patients." (PMID 31613226, 2019). "We identified the integrin αvβ3/CDC42/F-actin/YAP-1/Nupr1/Nestin signaling pathway, which was independent of the PI3K/AKT signaling in 3D collagen/FN cultured glioma cells." (PMID 33408794, 2021).
ependymoma (77 papers, 2015 to 2025). A WHO grade II, slow growing tumor of children and young adults, usually located intraventricularly. "These molecular categories demonstrate stronger correlations with prognosis than traditional histopathology: PFA tumors in children show poor survival, while PFB tumors and YAP1-driven supratentorial ependymomas are associated with more favorable outcomes." (PMID 41464145, 2025). "In contrast to RELA-fused tumors associated with adverse outcomes, YAP1-MAMLD1 fused ependymomas show an excellent prognosis." (PMID 33481105, 2021). "The presence of RELA and YAP1 fusion transcripts is the hallmark of supratentorial ependymomas, and 11q chromosomal alterations are frequently associated with complex gene rearrangements." (PMID 33228790, 2020). "Recurrent RELA and YAP1 fusions are intimately associated with tumorigenesis in supratentorial ependymomas." (PMID 33228790, 2020). "Here we show that forced expression of the most frequent ependymoma YAP1 fusion variant, YAP1-MAMLD1, is sufficient to form tumors in the developing mouse brain." (PMID 31477715, 2019). "Although the driven mutations of the supratentorial ependymoma (ZFTA fusion-positive or YAP1 fusion-positive) and posterior fossa ependymoma (either group PFA or PFB) are fully elucidated, according to the WHO 2021 classification, there is still no efficient treatment to control them." (PMID 37370764, 2023). "YAP1 fusion tumors represent a small fraction of supratentorial ependymomas and are predominantly observed in infants." (PMID 40556668, 2025). "This new classification includes supratentorial ZFTA-fusion-positive ependymoma, supratentorial YAP1-fusion-positive ependymoma, posterior fossa ependymomas groups PFA and PFB, spinal ependymoma, and MYCN-amplified spinal ependymoma." (PMID 40864821, 2025). "In pediatric patients, the key subtypes include posterior fossa ependymoma Group A (PF-A) and Group B (PF-B), as well as supratentorial ependymomas with RELA fusion or YAP1 fusion." (PMID 41417285, 2025). "Regarding the supratentorial ependymomas with confirmed ZFTA fusion regularly pose a worse prognosis when they are compared to those with YAP1 fusion." (PMID 40677455, 2025). "The ependymomas are classified on the basis of specific gene alterations, such as ZFTA or YAP1 fusions being characteristic in supratentorial ependymomas, and MYCN amplification being the norm in spinal ependymomas." (PMID 40677455, 2025). "Numerous widespread dot-like EMA-positive cells have been suggested as a characteristic feature of YAP1-fusion ependymomas." (PMID 41464145, 2025). "Two variants of supratentorial ependymoma have been characterized by specific molecular alterations: ZFTA fusion-positive (ST-EPN-ZFTA) and YAP1 fusion-positive (ST-EPN-YAP1)." (PMID 41050069, 2025). "YAP1::MAMLD1 gene fusions define one subtype of supratentorial ependymoma while ZFTA fusions define a more aggressive subtype." (PMID 40491864, 2024). "Both ZFTA and YAP1 fusion-positive ependymomas are demarcated from adjacent brain, with small- to medium-sized round nuclei." (PMID 37519792, 2023). "While ependymomas often have similar histologic features regardless of location, their molecular alterations are distinct with ZFTA and YAP1 fusions seen in supratentorial ependymomas and MYCN amplification in a subset of spinal ependymomas." (PMID 36969278, 2023). "Available data from retrospective analysis suggest a more favorable outcome for YAP1 fusion supratentorial ependymomas compared to ZFTA." (PMID 36617415, 2023). "Supratentorial ependymomas are divided into subependymoma (rare in children) and ependymomas with fusions involving ZFTA (an update to a pre-existing entity) or YAP1 (a new entity added for WHO CNS 5)." (PMID 36617415, 2023). "In a large retrospective analysis, children with YAP1 fusion-positive ependymomas had more favorable outcomes than those of other supratentorial ependymoma subtypes." (PMID 37509034, 2023).